CHGA (chromogranin A)
Diseases named in the same sentence as CHGA in open-access papers (continued):
Sharing a sentence is not in itself a finding about the gene and the disease.
prostate adenocarcinoma (7 papers, 2010 to 2024). "A widely used pan‐neuronal marker notwithstanding, TUBB3 expression was not related to neuroendocrine differentiation (NED, defined as positivity of generic NE markers chromogranin A and synaptophysin) in conventional prostate adenocarcinoma (p = 0.653)." (PMID 34318630, 2021). "According to an immunohistochemical analysis, he tested negative for PSA, NKX3.1, and p501s, the common markers of prostatic adenocarcinoma, but was tested positive for synaptophysin and chromogranin A." (PMID 31631483, 2019).
Alzheimer disease (6 papers, 2005 to 2025). A progressive, neurodegenerative disease characterized by loss of function and death of nerve cells in several areas of the brain leading to loss of cognitive function such as memory and language. "Moreover, previous studies have reported CHGA downregulation in Alzheimer’s disease and its presence in cerebellar unipolar brush cells, further supporting its relevance to neurocognitive health." (PMID 41018225, 2025). "In contrast, chromogranin A was seen only in amyloid β plaques of Alzheimer's disease." (PMID 16321154, 2005). "Interestingly, among the deregulated proteins associated to Alzheimer’s disease, we found previously reported AD-associated proteins, including the accumulation of GATA4 and Chromogranin-A, or MBL2, whose over-expression has been described in the surrounding of blood vessels in AD brain patients." (PMID 29541381, 2018). "Reduced CHGA (as well as VGF and cystatin C) levels were found in a proteomic analysis of CSF of patients with Alzheimer’s disease." (PMID 22970211, 2012). "Previous studies in ALS CFS mainly describe downregulation of chromogranin A but without sufficient discriminatory power and reduction has also been detected in CSF of patients with Alzheimer’s disease." (PMID 38687737, 2024).
gastroenteropancreatic neuroendocrine neoplasms (5 papers, 2013 to 2024). "Chromogranin A (CgA) is a well-established marker for diagnosis and follow up of patients with gastroenteropancreatic neuroendocrine neoplasms (GEP-NEN)." (PMID 29232390, 2017). "Chromogranin A (CgA) not only plays an important role in pathologic diagnosis, but is also used as a circulating biomarker in patients with gastroenteropancreatic neuroendocrine neoplasm (GEP-NEN)." (PMID 25501094, 2014). "A study suggested that SRS is more sensitive, more specific, and more accurate than chromogranin A (CgA) levels (a recognized marker for carcinoid tumours) for metastatic evaluation of carcinoid tumours." (PMID 23997766, 2013). "Failure to detect cytokeratin within tumour cells ruled out biliary carcinoma, and the lack of chromogranin A ruled out a carcinoid tumour." (PMID 31038324, 2019).
gastroenteropancreatic neuroendocrine tumors (5 papers, 2012 to 2018). "Chromogranin A (CgA), present in the chromaffin granules of neuroendocrine cells, is a useful biomarker for the diagnosis of patients with gastroenteropancreatic neuroendocrine tumors (GEP-NETs)." (PMID 27159453, 2016). "Chromogranin A (CgA) and the Ki-67 proliferation index are considered as important biochemical and pathological markers for clinical behaviour of gastroenteropancreatic neuroendocrine tumors (GEP NETs), respectively." (PMID 24042314, 2013). "Characteristics of 49 patients with liver metastases from gastrointestinal neuroendocrine tumor grade 1 and 2; AP: Alkaline phosphatase, CGA: Chromogranin A, 5HIAA: Urinary 5 hydroxy-indole acetate acid; ULN: Upper limit of normal; mets: Metastases; D-Pas: Duodeno-pancreas." (PMID 28562682, 2017).
hepatocellular carcinoma (5 papers, 2012 to 2023). A malignant tumor that arises from hepatocytes. "The aim of this work was to investigate the role of serum concentration of chromogranin A in patients with hepatocellular carcinoma at different stages." (PMID 23173843, 2012). "The neuroendocrine character has been observed in some tumor cells within some hepatocellular carcinoma nodules and elevated serum chromogranin A also been reported in patients with hepatocellular carcinoma." (PMID 23173843, 2012). "The chromogranin A levels in the Barcelona staging of hepatocellular carcinoma was higher in stage D compared to stage C (p<0.01), to stage B (p<0.001), and to stage A (p<0.001)." (PMID 23173843, 2012). "The chromogranin A serum levels were elevated (> 100 ng/ml) in 72/96 patients with hepatocellular carcinoma." (PMID 23173843, 2012). "Molecular markers, such as chromogranin A, could be very useful tools for hepatocellular carcinoma diagnosis." (PMID 23173843, 2012).
lung NETs (5 papers, 2009 to 2025). "The aim of this study was to evaluate the diagnostic effectiveness of pro-gastrin-releasing peptide (ProGRP) and chromogranin A (CgA) in the diagnosis of neuroendocrine neoplasms of the lung (LNENs), (290 cases) and compared these results with controls (54 cases)." (PMID 37444393, 2023). "Comparisons of pulmonary neuroendocrine tumors (PNET) and other groups with ROC analysis in terms of progastrin-releasing peptide (ProGRP), neuron-specific enolase (NSE), adjusted NSE, chromogranin A (CgA), and squamous cell carcinoma antigen 1 (SCCA1) values." (PMID 31091854, 2019). "Progastrin-releasing peptide (ProGRP), neuron-specific enolase (NSE), NSE adjusted, chromogranin A (CgA), and squamous cell carcinoma antigen 1 (SCCA1) values in the pulmonary neuroendocrine tumors (PNET), non-small-cell lung carcinoma (NSCLC), benign, and healthy groups." (PMID 31091854, 2019).
Obesity (5 papers, 2017 to 2025). Accumulation of substantial excess body fat. "We report here that obesity is associated with an increase of duodenal chromogranin A, GLP‐1, and serotonin‐expressing cells." (PMID 40790227, 2025). "Decreased EECs in obesity were also directly demonstrated by sorting the CHGA-positive cells in the mucosa by flow cytometry and by immunofluorescence staining of CHGA-positive cells in mucosal sections of CD versus HFD rats." (PMID 40806213, 2025). "Compared to controls, the patients with obesity showed significantly higher proportions of chromogranin A (p = 0.007), GLP‐1 (p = 0.006), and serotonin (p = 0.013) expressing cells, irrespective of T2D status." (PMID 40790227, 2025). "In conclusion, obesity was associated with hyperplasia of duodenal GLP‐1, serotonin, and chromogranin A cells." (PMID 40790227, 2025). "The impaired differentiation process in enteroids from patients with obesity was also evidenced by less outward protruding crypts and resulted in an enteroid population with less CHGA+ cells." (PMID 38125020, 2023). "Whole-mount immunostaining confirmed that protein expression for the pan-EEC marker, CHGA, was reduced (p < 0.05) with 80 ± 2% after treatment with 1 mM SCFAs at day 4 of differentiation in enteroids from patients with obesity." (PMID 38125020, 2023). "As already discussed for chromogranin A expression patterns, differences in methods and the composition of the cohorts in terms of severity of obesity and dysglycemia may explain the discrepant observations." (PMID 40790227, 2025). "In conclusion, our study shows that class 2 and 3 obesity with or without T2D is associated with an increase in duodenal chromogranin A, GLP‐1, and serotonin‐expressing cells." (PMID 40790227, 2025). "Chromogranin A, a component of neuroendocrine granules, is a general marker of intestinal neuroendocrine cells and may have a regulatory role in metabolism Numbers of chromogranin A expressing cells were about 40% higher in patients with obesity as compared with the controls." (PMID 40790227, 2025). "We characterized the overall duodenal endocrine cell population by using chromogranin A as a marker and focused on endocrine factors related to the incretin effect (GLP‐1) and other factors with suspected roles in obesity and metabolism (serotonin)." (PMID 40790227, 2025). "In a diet-induced rat model of obesity (HFD-induced obesity in Sprague Dawley rats), our results showed decreased mRNA and protein levels of the EEC marker CHGA, suggesting decreased EEC number." (PMID 40806213, 2025). "The number of EECs was calculated in tissue sections stained with chromogranin A, a marker of EECs, in the jejunum pre- and post-RYGB in subjects with obesity." (PMID 38910871, 2024). "In enteroids from patients with obesity, SCFAs (1 mM) increased (p < 0.05) ALPI mRNA expression 2.9-fold, but decreased (p < 0.01) MUC2 (0.4-fold) and CHGA (0.3-fold) mRNA expression." (PMID 38125020, 2023). "Although obesity did not affect CHGA mRNA expression, a significant reduction (p < 0.05) in the population of CHGA+ cells was found at the end of differentiation in enteroids from patients with obesity compared to normal weight individuals." (PMID 38125020, 2023). "In enteroids from patients with obesity, treatment with the HDAC inhibitor SAHA induced an increase (p < 0.05) in ALPI (3.9-fold) mRNA expression and a decrease (p < 0.01) in MUC2 (0.2-fold) and CHGA (0.2-fold) mRNA expression." (PMID 38125020, 2023). "In the current study, we first determined the effects of obesity on the expression of the transcription factors (MATH1, NGN3, and NeuroD1) that govern EEC differentiation from ISC, which subsequently affect the generation of chromogranin A (CHGA)-positive EECs." (PMID 40806213, 2025).
Obesity (continued). "Since chromogranin A labels most of the intestinal neuroendocrine cells, we were interested in assessing whether the ratios of the GLP‐1 and serotonin expressing cells with the chromogranin A expressing cells are related to obesity or T2D." (PMID 40790227, 2025). "In addition, we saw positive correlations between the GLP‐1/chromogranin A ratio and the determinants of defective glucose homeostasis, such as HbA1C and glucose AUC of the meal test among patients with obesity, but a negative correlation with blood glucose and insulin levels in the controls." (PMID 40790227, 2025). "We quantified expression of chromogranin A, glucagon‐like peptide‐1 (GLP‐1), serotonin, and neuromedin U (NmU) in duodenal biopsies from 34 participants with obesity (19 with T2D, 15 without) and six healthy controls." (PMID 40790227, 2025). "Human studies comparing numbers of small intestinal chromogranin A, GLP‐1 and serotonin expressing cells in healthy subjects and in those with obesity with or without T2D." (PMID 40790227, 2025).
pancreatic neuroendocrine neoplasm (5 papers, 2018 to 2023). A neoplasm with neuroendocrine differentiation that arises from the pancreas. "Common to neuroendocrine neoplasms of the pancreas is their expression of synaptophysin, chromogranin A, and/or INSM1." (PMID 34647171, 2022).
prostate tumor (5 papers, 2013 to 2021). "NE phenotype prostate tumor cells in TRAMP mice display similar morphological and molecular characteristics to human NED and NEPC cells, including the expression of IHC markers, synaptophysin, chromogranin A and FOXA2, and loss of expression of cytokeratin 8 (CK8)." (PMID 23620793, 2013). "Immunohistochemical stains of the primary prostate tumor demonstrated positive staining of the AR, NKX3.1, and PSMA, and negative staining for neuroendocrine (NE) markers synaptophysin, chromogranin A, and DLL3." (PMID 34385567, 2021). "To better understand this mechanism we investigated the co-expression of Brachyury with chromogranin A (CHGA) and synaptophysin (SYP) in silico, two NEtD markers described to distinguish prostate tumors with NE features." (PMID 27049720, 2016).
renal cell carcinoma (5 papers, 2010 to 2022). "The purpose of the study was to examine serotonin, CD56, neurone-specific enolase (NSE), chromogranin A and synaptophysin by immunohistochemistry in renal cell carcinomas (RCCs) with special emphasis on patient outcome." (PMID 20462442, 2010). "Immunohistochemical staining was positive for the cytokeratins, AE1 and AE3, and negative for CD56, chromogranin A, synaptophysin, renal cell carcinoma marker, and CD10." (PMID 27549181, 2016). "In contrast, thyroid transcription factor 1 (TTF-1), anti-renal cell carcinoma (RCC), CD10, CK20, as well as synaptophysin, chromogranin A, thyroglobulin and transthyretin are negative." (PMID 35546652, 2022).
squamous cell carcinoma (5 papers, 2019 to 2024). A carcinoma arising from squamous epithelial cells. "Nevertheless, the results of our present study confirmed the fact that poorly differentiated/basaloid squamous cell carcinomas must be differentiated from esophageal small-cell carcinomas by means of neuroendocrine markers (synaptophysin/chromogranin A) and a squamous-basal marker (e.g., p40)." (PMID 32556556, 2021).
adenoma (4 papers, 2013 to 2025). A neoplasm arising from the epithelium. "Focusing on the promoter methylation status of the neuroendocrine markers chromogranin A (CgA), chromogranin B (CgB) and CD56 (NCAM1) confirmed congruently lower methylation levels in NETs and PitNETs/adenomas compared to adenomas." (PMID 41060331, 2025). "Adenoma cultures contained scattered goblet-like cells judged by MUC2 staining, but appeared to lack CHGA+ cells consistent with previous observations and stainings on the corresponding primary tumor material." (PMID 24144042, 2013). "Moreover, CA1, CHGA, and GCG decreased significantly from normal to adenoma and continued to decrease significantly from adenoma to carcinoma, indicating that these genes continued to play a role in inhibiting the process from normal to adenoma then to carcinoma." (PMID 36944972, 2023).
Atrophic Gastritis (4 papers, 2017 to 2026). "Elevated circulating concentrations of chromogranin A can be found in renal and hepatic impairment, chronic atrophic gastritis, proton pump inhibitor use and inflammatory bowel disease." (PMID 33391185, 2020). "In contrast to the location of gastric atrophy, gastric ghrelin is produced in the chromogranin A-immunoreactive X/A-like endocrine cells located in the mucosal layer of the fundus." (PMID 28419119, 2017). "The sensitivity and specificity limitations of chromogranin A may depend on the test used and clinical situations, such as secondary hypergastrinemia, gastrinoma, atrophic gastritis, Helicobacter pylori infection, use of proton pump inhibitors and liver or kidney dysfunction." (PMID 28194228, 2017).
colitis (4 papers, 2017 to 2024). Inflammation of the colon. "We previously demonstrated that CHGA is implicated in colitis progression by regulating the macrophages." (PMID 33121008, 2020). "This follows the data demonstrating that CHGA and its derived peptides play a significant role in macrophages activation during colitis progression." (PMID 33535452, 2021). "Previously, we demonstrated that CHGA and its derived peptides modulate macrophages’ functional activity during colitis progression; therefore, herein, we determined if PST can directly modulate AAM’s polarization." (PMID 33535452, 2021). "Conversely, the lack of CHGA in Chga-deficient mice demonstrated a reduction in the colitis severity associated with an increase in AAM’s polarization, implying the existence of a dominant proinflammatory CHGA-derived peptide." (PMID 33535452, 2021). "Hyperplasia of enterochromaffin cells and elevated levels of CHGA have been reported in UC and CD patients and animal models of colitis, demonstrating that CHGA plays a potentially important role in regulating intestinal inflammation through various targeted mechanisms." (PMID 33121008, 2020). "To explore the relationship between CHGA and those markers, we used Chga−/− mice and a DSS model of colitis." (PMID 33121008, 2020). "However, protein levels of CHGA declined, and those of Dclk1 increased in PSTi8-treated female mice compared to in PBS-treated female mice in colitis." (PMID 39684467, 2024). "In preclinical and clinical settings, CHGA level is increased and is correlated with the clinical severity of gastrointestinal inflammation in IBD patients and in murine experimental models of colitis." (PMID 33535452, 2021). "We further described the effects of the lack of CHGA on functional epithelial markers in a UC-like dextran sulphate sodium (DSS) model of colitis." (PMID 33121008, 2020). "Although the possible impact of elevated ChgA in gut inflammation remains unknown, our group for the first time, showed that hCTS derived from the distal portion of ChgA is increased both in IBD and experimental colitis mouse models." (PMID 28871257, 2017). "Moreover, we and others demonstrated that PST supplementation in the CHGA-knockout mice model increases the intestinal mucosal permeability at a steady state, reduces TJ mRNA expression and worsens disease severity in the dextran sodium sulfate (DSS) experimental model of colitis." (PMID 39684467, 2024).
dementia (4 papers, 2011 to 2023). Loss of intellectual abilities interfering with an individual's social and occupational functions. "Other candidate biomarkers related to neurodegeneration are chromogranin-A and secretogranin-1, which are characterized by elevated concentrations in MCI and decreased concentrations in dementia." (PMID 33671562, 2021).
inflammatory bowel disease (4 papers, 2017 to 2025). A spectrum of small and large bowel inflammatory diseases of unknown etiology. "While there is growing awareness of a relationship between chromogranin-A (CHGA) and susceptibility to inflammatory conditions, the role of human catestatin [(hCTS); CHGA352–67] in the natural history of established inflammatory bowel disease is not known." (PMID 28871257, 2017).
lung carcinoids (4 papers, 2014 to 2024). "The diagnosis of lung carcinoid tumors requires data on neuroendocrine differentiation, which is recognized by positive immunohistochemical (IHC) stains for Ki-67, mTOR, and chromogranin A." (PMID 33557782, 2021). "From an immunohistochemical viewpoint, lung carcinoids are positive for pan-cytokeratins and neuroendocrine markers of first- (CD56, chromogranin A, and synaptophysin) and second-generation lineages (INSM1)." (PMID 38001701, 2023).
lymphoma (4 papers, 2019 to 2025). A malignant (clonal) proliferation of B- lymphocytes or T- lymphocytes which involves the lymph nodes, bone marrow and/or extranodal sites. "A broad panel of immunohistochemistry excluded lymphoma and nephroblastoma, confirming extra-adrenal paraganglioma based on strong positivity for anti-synaptophysin, neuron-specific enolase, chromogranin A, and cytokeratin 19 antibodies." (PMID 40948633, 2025). "Immunohistochemistry staining showed positivity for NSE, synaptophysin, chromogranin A, CD56, S100 protein neurofilaments, calretinin, and glial fibrillary acidic protein and was negative for epithelial and lymphoma markers." (PMID 40821301, 2025).
Merkel cell carcinoma (4 papers, 2004 to 2022). "All tumors included in the present study exhibited the classic morphology of Merkel cell carcinoma and expressed diffusely chromogranin A, synaptophysin, and cytokeratin 20 (dot-like expression pattern)." (PMID 36298750, 2022). "Merkel cell carcinomas also label for neuron specific enolase (virtually all), chromogranin B (100%), chromogranin A (72%), secretoneurin (22%), and synaptophysin (39%)." (PMID 15550173, 2004). "ChgA protein levels have been proposed to assist in the diagnosis of Merkel cell carcinoma patients who may benefit from oncological therapy." (PMID 17173689, 2006).
pituitary tumor (4 papers, 2016 to 2025). A benign or malignant neoplasm affecting the pituitary gland. "Histological and immunohistochemical analysis confirmed loss of menin expression in pituitary tumours (n = 4) from C57BL/6 Men1+/- and 129S6/SvEv Men1+/- mice and expression of prolactin, growth hormone and chromogranin A." (PMID 32348957, 2020). "As in the pancreas, pituitary tumors were positive for chromogranin A." (PMID 27769070, 2016). "Pituitary tumors expressed chromogranin A and closely resembled human pituitary adenomas." (PMID 27769070, 2016). "Immunohistochemical staining of the pituitary tumor demonstrated positive for ACTH, chromogranin A, and synaptophysin, with Ki-67 index at 3%." (PMID 40213016, 2025).